INS (insulin)
Diseases named in the same sentence as INS in open-access papers (continued):
Sharing a sentence is not in itself a finding about the gene and the disease.
Insulin resistance (continued). "Once insulin over-secretion can no longer compensate for the degree of insulin resistance, hyperglycemiabecomes clinically significant and deterioration of residual β-cell reserve accelerates." (PMID 24524730, 2014). "Once insulin secretion by the pancreatic islet β-cells can not compensate adequately for the degree of insulin resistance, hyperglycemia and DM2 are established." (PMID 25268492, 2014). "In states of hepatic insulin resistance, these enzymes are not suppressed by insulin and result in elevated endogenous glucose production which contributes to hyperglycemia." (PMID 24520329, 2014). "In vivo, increased GSK3 activity is an early event in the development of insulin resistance where glycogen synthesis is impaired in type 2 diabetes and inhibition of GSK3 in Zucker diabetic fatty rats leads to an improvement in both insulin action and glucose uptake." (PMID 25541965, 2014). "As shown in Section 2.1, these markers include ICA, IAA, GAD, ICA 512, MIAA, fasting glucose, HbA1c, fasting insulin, first-phase insulin response (FPIR), Homeostasis model assessment of insulin resistance (HOMA-IR), and 2 hr glucose, fasting glucose, C-Peptide measurements." (PMID 24926781, 2014). "Fasting glucose, insulin, and insulin resistance measured by the HOMA-IR index were not different between the start and end of treatment." (PMID 24659984, 2014). "Consequently, the homeostatic model assessment for insulin resistance (HOMA-IR) was higher in these animals, indicating a decrease in insulin sensitivity as a consequence of the CAF diet intake." (PMID 24482678, 2014). "Adiponectin was directly and linearly associated with PEA (β = 0.62 ± 0.28, p = 0.03) among non-obese (n = 673) and insulin sensitive participants (n = 1141; β = 0.74 ± 0.23, p = 0.001), but not among those obese or with insulin resistance." (PMID 24575123, 2014). "Insulin resistance (IR) plays a pivotal role in the pathogenesis of both PCOS and GDM, representing an important therapeutic target, with metformin being the most widely prescribed insulin-sensitizing antidiabetic drug." (PMID 25763406, 2014). "IGF-1 concentration is directly related to insulin sensitivity, irrespective of confounders such as age, BMI, WHR or glucose tolerance status, but its association to insulin resistance seems U shaped." (PMID 24736741, 2014). "We investigated whether MH affects HFD-induced insulin resistance, showing that HFD feeding increased fasting blood glucose and plasma insulin levels, consistent with previously published data." (PMID 24991305, 2014). "The association of leptin with hyperglycemia and its significant correlation with serum glucose and insulin levels in PCOS thus explain its role in metabolic impairments, which may occur due to insulin resistance." (PMID 25587271, 2014). "Insulin resistance is therefore best measured using “clamp” techniques, such as the HIEC, which provides an accurate index of cell-mediated glucose uptake via the action of insulin, and is therefore considered the “gold standard” test of insulin resistance." (PMID 25254366, 2014). "As a result, although EGP and its suppression by insulin did not significantly differ between subgroups, the hepatic insulin resistance index was higher in the high liver fat subgroup." (PMID 25104497, 2014). "In cultured cells, development of insulin resistance induced by a pathological level of insulin was prevented in the absence of fat." (PMID 25055153, 2014). "Some studies have shown PEDF to inhibit AGE-induced hepatic insulin resistance and restore the reduced adiponectin levels in AGE-exposed adipocytes, whereas others have suggested that PEDF could induce insulin resistance in muscle and fat cells." (PMID 25166721, 2014).
Insulin resistance (continued). "The depletion of glypican-4 reduces insulin signaling, whereas the overexpression of wild-type glypican-4 enhances the insulin-mediated phosphorylation of ERK and AKT, indicating its potential role as a target for the treatment of insulin resistance." (PMID 24633815, 2014). "The explanation for these results are complex, however experimental studies have shown that in mice with total insulin resistance in liver, insulin fails to stimulate the synthesis of fatty acids and triglycerides." (PMID 25474087, 2014). "In that report, animals exposed to 10 μg/kg/day presented glucose intolerance and insulin resistance while those exposed to 100 μg/kg/day were glucose intolerant with no change in insulin sensitivity." (PMID 24959901, 2014). "Homeostasis model assessment of insulin resistance (HOMA-IR), calculated by fasting glucose (mmol/l) x fasting insulin (IU/ml)/22,5 and QUICKI, calculated by 1/log (fasting insulin (IU/ml)) + log (fasting glucose (mg/dl)), will be used to evaluate insulin resistance." (PMID 25033925, 2014). "When insulin resistance occurs, the normal amount of secreted insulin is not sufficient in order to deliver glucose into the cells." (PMID 24812607, 2014). "We aim to confirm whether inhibiting GHR under baseline conditions can alter the post-receptor activity of GH and insulin signaling, and explore the possible mechanisms linking CUG and insulin resistance in SGA." (PMID 24963636, 2014). "At baseline (week-33 to 36 of gestation), obese women with and without GDM had significantly increased levels of fasting insulin and C-peptide compared to lean subjects and showed increased insulin resistance estimated by HOMA-IR-index." (PMID 24720885, 2014). "Third, the serum insulin and leptin level, hepatic and peripheral insulin resistance were not measured in the current study." (PMID 24598574, 2014). "Moreover, insulin resistance of adipose tissue leads to an enhanced FFA flux to the liver, for example, in contribution to insulin resistance and steatosis." (PMID 25295245, 2014). "Having matched case and control groups, this study calculated resistance to insulin using HOMA-IR index and found that the case group differed significantly in levels of insulin resistance both before and after the development of preeclampsia in comparison to the control group." (PMID 24812607, 2014). "In accordance with previous studies showing that GC induces insulin resistance and glucose intolerance, the HOMA and the TyG indexes and ipGTTs revealed a significant reduction in insulin sensitivity and glucose tolerance in the DEX rats compared with the control rats (respectively)." (PMID 24705399, 2014). "During hepatic insulin resistance, hepatic glucose production is no longer downregulated by insulin, resulting in increased hepatic glucose production and stimulation of increased insulin secretion." (PMID 24563869, 2014). "Calculated indicators of insulin resistance were not significantly different between groups and were on the verge of defining insulin or indicated insulin resistance for both groups." (PMID 24711817, 2014). "Moreover, the effects of PKCθ on insulin signaling are mediated through activation of IKK, a kinase that promotes insulin resistance." (PMID 24819750, 2014). "Insulin resistance and β-cell function are inversely correlated with thyroid stimulating hormone (TSH) which may be explained by insulin-antagonistic effects of thyroid hormones along with an increase in TSH." (PMID 25162051, 2014). "The HMW:TA ratio also correlated negatively with waist, waist hip ratio (data not shown), fasting insulin levels and BMI (data not shown) - all markers of insulin resistance." (PMID 25580091, 2014). "This clearly demonstrates that insulin sensitivity is not required for extended longevity – and that insulin resistance, although perhaps undesirable, is not sufficient to block extended longevity." (PMID 25674466, 2014).
Insulin resistance (continued). "Although rapamycin treatment did not improve glucose intolerance, homeostatic model for assessment of insulin resistance (HOMA-IR) values derived from both insulin and glucose levels were significantly reduced, indicating higher insulin sensitivity which was confirmed by an insulin tolerance test." (PMID 24710396, 2014). "Since plasma insulin level is often higher in patients with T2DM compared with non-diabetic individuals, T2DM is characterized by obesity, hyperinsulinemia, and insulin resistance; however, the significance of beta cell dysfunction in patients with T2DM has been often ignored." (PMID 26237486, 2014). "Demographic data, glucose levels, insulin levels, lipid profiles, homeostasis model assessment for β cell function index (HOMA-β), homeostasis model assessment for insulin resistance index (HOMA-IR), and quantitative insulin-sensitivity check index (QUICKI) were compared between the two groups." (PMID 24829924, 2014). "al induced acute insulin resistance by constant infusion of Intralipid (a fat emulsion) and lactate for 5 h in rats, resulting in 2 to 3 fold higher PDK4 expression in muscle following insulin infusion, indicating the impaired ability of insulin to suppress PDK4." (PMID 24520982, 2014). "Although scarcely studied, the influence of triiodothyronine (T3; free or total) seems to be negative for obesity, insulin concentration, insulin resistance, systolic and diastolic blood pressure, and dyslipidemias, but is favored by hyperglycemia." (PMID 24936390, 2014). "No ethnic difference was noted in calculated measures of insulin resistance such as area under the curve (AUC) for insulin or the insulinogenic index." (PMID 23607267, 2013). "As FFA regulate insulin sensitivity, an impairment in NPY's antilipolytic action could lead to changes in insulin resistance." (PMID 24106499, 2013). "Both TNF-α and IL-6, two main proinflammatory cytokines released by adipose tissue, can inhibit insulin signalling, and TNF-α may have a crucial role in the development of insulin resistance in type 2 diabetes." (PMID 23590862, 2013). "FGF21 has potential insulin mimetic effects on lowering plasma glucose and liver lipid levels, suggesting that FGF21 may play a role in the pathogenesis of liver and whole-body insulin resistance in T2DM17." (PMID 24189525, 2013). "Since deletion of SH2B1 in the entire peripheral tissues exacerbates HFD-induced insulin resistance and glucose intolerance in TgKO mice, SH2B1 in other peripheral tissues (e.g. skeletal muscle and/or adipose tissue) is likely to promote insulin regulation of glucose metabolism." (PMID 24358267, 2013). "When there is insulin resistance, beta cells compensate for the insulin resistance by increasing insulin secretion even in the presence of normal glucose concentrations." (PMID 23983807, 2013). "Although the affinity of insulin for type I IGF receptor is low, the supraphysiological concentrations of insulin present in obese people with insulin resistance and hyperinsulinaemia and in those with the metabolic syndrome are probably sufficiently high to signal through this receptor." (PMID 23983688, 2013). "Recent evidence has shown that plasma LPL has significant correlation with insulin sensitivity but negative correlation with insulin resistance and fasting insulin sensitive index." (PMID 24086538, 2013). "The different behaviour of insulin-stimulated versus non-insulin stimulated cells to rosiglitazone has important bearing in hyperinsulinaemic states which often occur in insulin resistance, though not always." (PMID 24391675, 2013). "We did not know the insulin resistance status of our patients, as insulin levels were not available to provide a calculation of HOMA-IR." (PMID 23621905, 2013). "Though insulin resistance was not directly measured in this study, we determined the balance between insulin, growth hormone, and prolactin as an indirect indication of this phenomenon." (PMID 24244349, 2013).
Insulin resistance (continued). "Insulin normally acts to suppress hepatic glucose production (HGP) by inhibiting gluconeogenesis and stimulating net glycogen synthesis, however, this ability is impaired in insulin resistance and T2D." (PMID 24150286, 2013). "Thus, LPS induce S-nitrosation/S-nitrosylation of the insulin signaling pathway (IR, IRS-1, and Akt), inducing insulin resistance in the liver, muscle, and adipose tissue in a more particular way than serine phosphorylation of IRS-1." (PMID 23840101, 2013). "Insulin tolerance tests did not reveal a significant improvement in either Pdk2 or Pdk4 knockdown mice although Pdk4 knockdown had a trend of improvement of insulin resistance." (PMID 23940800, 2013). "While several studies indicate that increased IL-6 levels correlate with adiposity and fat mass, and not necessarily with insulin action or responsiveness, another study has pointed to higher IL-6 levels in patients with obesity-related insulin resistance." (PMID 24455420, 2013). "develops in the second, partially uncompensated phase of insulin resistance when the enhanced insulin synthesis of pancreatic islet cells is not enough to maintain euglycemia." (PMID 23061769, 2013). "The activation of these kinases has a negative feedback on proximal insulin signalling, contributing to insulin resistance and to a hyperinsulinemic state that further increases de novo liponeogenesis, hepatic lipid accumulation and disease progression." (PMID 24084730, 2013). "Our findings of increased insulin and HOMA-IR suggest a tendency towards insulin resistance." (PMID 23575345, 2013). "Although insulin resistance contributes to the pathogenesis of T2DM, it is the failure of pancreatic β-cells to secrete sufficient insulin to maintain normoglycemia, due to a decrease in β-cell function and mass, that results in the development of T2DM (for reviews see:1, 2, 3)." (PMID 24145577, 2013). "On the other hand, overexpression of PTEN has been shown to have inhibitory effects on insulin signaling, including decreased AKT activity and GLUT4 (glucose transporter 4) translocation to the cell membrane, showing the contribution to insulin resistance and then NAFLD progression." (PMID 23431468, 2013). "It is becoming increasing apparent that ceramide plays significant role in insulin resistance, a metabolic state in which cells fail to respond to the normal hormonal actions of insulin." (PMID 23835113, 2013). "However, direct evidence from insulin tolerance test and glucose tolerance test on rats are essential to validate the possible beneficial effects of SAMC on insulin resistance." (PMID 22278044, 2013). "In the diabetic group adiponectin correlated positively with serum glucose, negatively with serum proinsulin and HOMA beta cell function (P = 0.03) respectively and serum ghrelin (P = 0.003), but not with BMI, HOMA insulin resistance, insulin or leptin." (PMID 23497407, 2013). "Although mechanisms by which MDSCs enhance insulin sensitivity are unknown, it has been proposed that upregulation of insulin growth factor-1 (IGF-1) in the setting of insulin resistance may lead to the accumulation of MDSCs or M2 macrophages." (PMID 24455420, 2013). "Time courses of body weight, systolic blood pressure, fasting plasma glucose (FPG), insulin, free fatty acids (FFA), homeostasis model assessment-insulin resistance index (HOMA-IR), thermal and mechanical sensitivity and motor coordination were measured in parallel." (PMID 23451227, 2013). "The acute worsening of insulin resistance, despite enhanced Akt phosphorylation and Akt-FoxO1 signaling, highlights that acute regulation of hepatic glucose production by insulin is unlikely to be mediated by transcriptional changes in gluconeogenic enzymes." (PMID 24150286, 2013).
Insulin resistance (continued). "A Cox regression model was applied to test for the associations between cancer mortality and fasting serum glucose, insulin, glycosylated hemoglobin (HbA1c), C-peptide, insulin like growth factor (IGF-1), IGF binding protein 3 (IGFBP3) and estimated insulin resistance." (PMID 23405181, 2013). "A correlation between insulin sensitivity and serum concentrations of RBP4 has, however, not been consistently reported, and a number of reports have questioned the role of RBP4 in insulin resistance." (PMID 23781325, 2013). "Additionally, were calculated homeostatic model assessment-insulin resistance (HOMA-IR) and quantitative insulin sensitivity check index (QUICKI)." (PMID 23443001, 2013). "As liver fat content is associated with insulin resistance in women with a history of GDM that is independent of obesity, it is possible that liver fat contributed to reduced insulin sensitivity in older women with a history of GDM." (PMID 23781323, 2013). "Nevertheless, BMI z-score is only one of the factors influencing the prepubertal rise in insulin resistance and, importantly, deterioration of insulin sensitivity at this age is not accompanied by worsening of the lipid profile." (PMID 23935878, 2013). "So far, few studies exploring the role of PTEN in insulin resistance have been conducted without involving the effect of insulin." (PMID 23840818, 2013). "In addition, fasting insulin levels were 3-fold lower in the LTKO mice as compared to the control mice, and homeostatic model assessment (HOMA) also showed 4-fold decrease in insulin resistance in the LTKO mice." (PMID 24015318, 2013). "Everolimus probably decreases insulin production and release from the pancreatic beta cells through the AMP-activated protein kinase (AMPK)/c-Jun N-terminal kinase (JNK)/FoxO pathway and it probably induces peripheral insulin resistance." (PMID 23738155, 2013). "Moreover, visceral and epidydimal fat contents correlate positively with insulin resistance, hence, phytol-mediated decrease in VFW/and EFW/BW ratios, offers another mechanism for improved insulin sensitivity." (PMID 23300941, 2013). "The major finding in the present study is that although resveratrol had effects on both reproductive and metabolic parameters, it did not restore insulin sensitivity in rats with androgen-induced insulin resistance." (PMID 23690868, 2013). "Insulin resistance index (HOMA-IR) rather than insulin secretion index (HOMA-β cell) was distinctively different between the two groups." (PMID 23825680, 2013). "The insulin resistance in TLR2 KO mice could be explained by the increased LPS serum levels, which lead to TLR4 activation in the insulin target organs." (PMID 24064574, 2013). "We showed that mice lacking endogenous insulin induced by STZ had similar insulin resistance after chronic GH treatment, but PTEN expression did not change." (PMID 23840818, 2013). "Even when controlling for age, however, the managed dolphins still had higher insulin and lipids compared to Sarasota Bay dolphins, supporting that age is not the sole driver of insulin resistance and metabolic syndrome in dolphins." (PMID 24133483, 2013). "Although the obese state generates peripheral insulin resistance in many tissues, not all insulin signalling is impaired." (PMID 23497533, 2013). "We show that serum vitamin D levels are negatively related to C3 and C4 concentrations, but these correlations were not maintained after adjustment for BMI, insulin levels, and insulin resistance." (PMID 23509804, 2013). "Impaired insulin-stimulated muscle glycogen synthesis plays a significant role in insulin resistance and noninsulin-dependent diabetes mellitus." (PMID 24454989, 2013). "Taken together, these findings suggest that elevations in plasma LPS concentration found in obese and T2DM subjects could play a role in the pathogenesis of insulin resistance and that antagonists of TLR4 may improve insulin action in these individuals." (PMID 23704966, 2013).